ENOX1 (ecto-NOX disulfide-thiol exchanger 1)
Description:
Probably acts as a terminal oxidase of plasma electron transport from cytosolic NAD(P)H via hydroquinones to acceptors at the cell surface. Hydroquinone oxidase activity alternates with a protein disulfide-thiol interchange/oxidoreductase activity which may control physical membrane displacements associated with vesicle budding or cell enlargement. The activities oscillate with a period length of 24 minutes and play a role in control of the ultradian cellular biological clock.
Synonyms: cCNOX; cNOX; PIG38; FLJ10094; bA64J21.1
Tractability: Antibody: UniProt places it where antibodies can reach, with high confidence; its Gene Ontology location is reachable by antibodies, with high confidence; the Human Protein Atlas places it where antibodies can reach. PROTAC: ubiquitination databases record sites on it; its protein half-life has been measured.
Gene: Protein-coding gene on chromosome 13 (43,213,004 to 43,787,328, reverse strand). Ensembl gene ENSG00000120658.
Subcellular location: Cell membrane; Secreted, extracellular space
Subcellular location (Human Protein Atlas): Plasma membrane
Gene Ontology:
Molecular function: NADH dehydrogenase activity; protein binding; protein disulfide isomerase activity; nucleic acid binding; RNA binding
Cellular component: plasma membrane; extracellular region
Genetic constraint (gnomAD): Loss-of-function variants: 35 observed, 74 expected, observed/expected ratio (o/e) 0.47, 90% interval 0.36 to 0.63. The upper end of that interval is the gene's LOEUF score, 0.63, which puts it in group 2 of 6, group 1 being the genes least tolerant of losing a copy. Missense variants: 560 observed, 798.27 expected, observed/expected ratio (o/e) 0.7, 90% interval 0.65 to 0.75. Synonymous variants: 247 observed, 277.58 expected, observed/expected ratio (o/e) 0.89, 90% interval 0.8 to 0.99.
Homologues: Orthologues: chimpanzee ENOX1 (100% identical), macaque ENOX1 (99% identical), guinea pig ENOX1 (98% identical), rat Enox1 (98% identical), dog ENOX1 (98% identical), mouse Enox1 (98% identical), pig ENOX1 (98% identical), rabbit ENOX1 (89% identical), tropical clawed frog enox1 (82% identical), zebrafish enox1 (70% identical), Drosophila melanogaster CG10948 (38% identical). Paralogues in human: ENOX2 (62% identical).
Diseases named in the same sentence as ENOX1 in open-access papers:
ENOX1 is named in the same sentence as 10 diseases in open-access papers, as found by Europe PMC text mining. Sharing a sentence is not in itself a finding about the gene and the disease. The quoted sentences say what the papers report.
schizophrenia (3 papers, 2016 to 2025). A major psychotic disorder characterized by abnormalities in the perception or expression of reality. "Phenotypically, ENOX1 has been associated with mental illnesses, such as schizophrenia, unipolar depression, and bipolar disease." (PMID 36012217, 2022). "Additionally, some SNPs of ENOX1 (ecto-NOX disulfide-thiol exchanger 1) gene where the identified rs9567245 SNP is located have been linked to MDD and schizophrenia." (PMID 40799755, 2025).
anorexia nervosa (1 paper, 2025). A disorder most often seen in adolescent females characterized by a refusal to maintain a minimally normal body weight, an intense fear of gaining weight, a disturbance in body image, and, in postmenarcheal females, the development of amenorrhea. "Furthermore, the PGC cross-disorder study on eight disorders (OCD, ADHD, ASD, MDD, TS, anorexia nervosa, bipolar disorder, and SCZ) identified SNPs of ENOX1 gene among the top SNPs." (PMID 40799755, 2025).
breast carcinoma (1 paper, 2025). "Both ENOX1 and PTBP1 evinced the same trend as the ensemble of these RBPs, that is, their expression levels are positively correlated with those of the associated TCNEs as well as breast cancer development." (PMID 40427520, 2025).
colon cancer (1 paper, 2021). "Further analysis revealed that ZC3H10, SAMD4A, and ENOX1 are closely related to anti-tumour immunity against colon cancer." (PMID 35155186, 2021).
myocardial infarction (1 paper, 2019). Gross necrosis of the myocardium, as a result of interruption of the blood supply to the area, as in coronary thrombosis. "Since the rs7242 G allele was associated with increased risk of myocardial infarction, the regulatory mechanisms between Enox1 and PAI‐1 needs further investigation." (PMID 31268630, 2019).
tumor (4 papers, 2016 to 2021). "Multi-fractionation irradiation of allograft and xenograft tumors was found to synergize with pharmacological targeting of Enox1 to reduce tumor microvascular density and decrease tumor growth." (PMID 27788492, 2016). "We interpret these results to indicate that targeting Enox1 in tumor stroma concurrently with radiotherapy can provide a survival advantage." (PMID 27788492, 2016). "Pharmacological targeting of Enox1 resulted in 80% of the tumor-bearing mice surviving at 90 days compared to only 40% of tumor-bearing mice treated with solvent control." (PMID 27788492, 2016). "Targeting of Enox1 in tumor stroma increased survival of tumor-bearing mice 2 fold when measured 90 days after irradiation." (PMID 27788492, 2016). "Four daily injections of VJ115 followed 30 min later by 2 Gy administered to the tumor resulted in a statistically significant decrease in Enox1/VE-Cadherin expression relative to radiation alone (≅5–fold, P = 0.026)." (PMID 27788492, 2016). "In summary, the data presented herein suggests that Enox1 regulation of tumor stroma radiosensitivity via NADH/NAD cellular metabolism can contribute significantly to tumor control and survival and identifies Enox1 as a potential therapeutic target." (PMID 27788492, 2016). "We interpret these results to indicate that pharmacological targeting of Enox1 in tumor stroma inflicted a significant degree of radiation-induced damage to tumor stroma that contributed to radiation-induced tumor control." (PMID 27788492, 2016). "The goal of this investigation was to clarify the question of whether targeting Enox1 in tumor stroma would synergistically enhance the survival of tumor-bearing mice treated with fractionated radiotherapy." (PMID 27788492, 2016). "Using this approach we investigated the question of whether concurrent x-irradiation and pharmacological inhibition of Enox1 in tumor stroma could increase the survival of HT29 tumor-bearing mice." (PMID 27788492, 2016). "Therefore, targeted inhibition of ENOX1 activity to inhibit tumor angiogenesis may be a feasible strategy for tumor control." (PMID 34239534, 2021). "We next addressed the question of whether VJ115 targeting of Enox1 would affect tumor control." (PMID 27788492, 2016). "Therefore, we focused on the question of whether concurrent x-irradiation and pharmacological inhibition of Enox1 in tumor stroma could increase the survival of HT-29 tumor-bearing mice." (PMID 27788492, 2016). "Significant correlation was observed between the polarised M2 macrophages and ENOX1, NCAM1, SAMD4A, and ZC3H10 with respect to tumour purity." (PMID 35155186, 2021). "The targeted genes, ENOX1, NCAM1, SAMD4A, and ZC3H10, are closely related to CRC tumour-infiltrating macrophages." (PMID 35155186, 2021). "In contrast to tumors, the adjacent non-tumor tissues harbored eight genes with recurrent HBV integration, including FN1, DCC, OAZ2, ANO3, ENOX1, GRIK4, NPAT, and SNCAIP." (PMID 34209079, 2021). "The HT-29 tumor model was used because these cells do not express Enox1 and they are not radiosensitized by pharmacological inhibition of Enox1." (PMID 27788492, 2016). "In the experiments undertaken in this investigation we used the small molecule inhibitor VJ115 that targets Enox1 in the tumor vasculature but does not radiosensitize HT-29 tumor cells." (PMID 27788492, 2016). "Enox1, a NADH oxidase, is expressed in tumor vasculature and stroma." (PMID 27788492, 2016).
cancer (2 papers, 2022 to 2025). A tumor composed of atypical neoplastic, often pleomorphic cells that invade other tissues. "ENOX1 inhibitors were studied for their anti‐angiogenic properties, potentially useful for treating cancer, but the possible effect of this type of drug on cognitive function has not been explored." (PMID 35488718, 2022). "The upregulation of interferon-related genes (Stat1, Irf1) suggests activation of antitumor immune responses, while downregulation of metabolic enzymes like Enox1 may indicate metabolic reprogramming of cancer cells." (PMID 40969227, 2025).
mental illnesses (2 papers, 2022). "In addition to associations with psychiatric disorders, a couple of previous studies reported associations between ENOX1 variants and cognition." (PMID 35488718, 2022).
ENOX1 also shares sentences with these, for which no sentence is quoted: bipolar disorder (1 paper); unipolar depression (1).